IL33 (interleukin 33)
Diseases named in the same sentence as IL33 in open-access papers (continued):
Sharing a sentence is not in itself a finding about the gene and the disease.
COVID-19 (continued). "Significantly lower expression of IL-33 was found in the lung tissue of COVID-19 patients compared with the control group, which may be related to the possibility of depletion of IL-33 as well as its degradation, which cannot be detected by commercially available antibodies." (PMID 37509486, 2023). "Therefore, exploring IL-22 and IL-33 in COVID-19 and their relationship to each other may expand our understanding of the pathogenic mechanism associated with the disease." (PMID 36875710, 2023). "Thus, IL-33 may induce T-bet-dependent differentiation of CD8+ T cells to form cytotoxic as well as memory CD8+ T cells in COVID-19 and upregulate CD8+ T-cell expression of GM-CSF, which may be responsible for neutrophil and monocyte activation in the tissues." (PMID 36362440, 2022). "Therefore, the same interaction between IL-33 and GM-CSF might occur in patients with COVID-19, initiating the cytokine storm syndrome." (PMID 36498859, 2022). "Therefore, IL-33 acts as a protagonist in maintaining and advancing lung inflammation, in which many innate pro-inflammatory cytokines, leading to the most severe forms of COVID-19, are involved." (PMID 36498859, 2022). "Therefore, targeting the intervention of IL-33/ST2/pDCs/IFN-I signaling pathway may provide new therapeutic opportunities for COVID-19." (PMID 36362440, 2022). "Thus, it can be speculated that blockade of the IL-33/Treg/Th17 signaling axis or the IL-6 receptor may then hold promise for the development of novel therapeutic strategies for COVID-19." (PMID 36362440, 2022). "In the presence of an adequate immune response and virus clearance, IL-33 may play a key role in driving rapid Treg-cell-dependent restoration of respiratory tissue homoeostasis, which explains the mild or asymptomatic cases of COVID-19." (PMID 36498859, 2022). "However, whether the interaction mechanism of IL-33 with pDC or IFN-I is involved in the pathological development of COVID-19 remains unknown." (PMID 36362440, 2022). "The IL-33/ST2 axis might play a leading role in COVID-19 pathogenesis." (PMID 34441830, 2021). "On a positive note, the ST2/IL-33 pathway could represent a potential therapeutic target for controlling excessive pulmonary and systemic inflammation in patients with moderate to severe forms of COVID-19, by using anti-ST2 antibodies such as astegolimab." (PMID 33530550, 2021). "Keeping in mind obtained data that IL-33 portrays an important role during severe form of COVID-19 followed by augmented inflammation, IL-33 might act as a promising therapeutic target which hinders COVID-19 severity." (PMID 34917631, 2021). "Higher levels of IL-3 and IL-33 cytokines in inflammatory environments explain the higher levels of CD25 expression in allergic patients, as well as in severe COVID-19 patients." (PMID 41459501, 2025). "Together, these findings suggest that IL3 and IL33 contribute to the upregulation of IL2RA and IL2RG on basophils in severe COVID-19." (PMID 41459501, 2025). "Importantly, both single viroporins and SARS-CoV-2 virus could induce IL-1α and IL-33 expression and release not only in pulmonary epithelial cell but also microvascular endothelium shedding novel light on the inflammatory response of endothelium in COVID-19." (PMID 38664396, 2024). "Compared with age-matched unexposed elderly individuals, convalescent COVID-19 patients presented with more IFN-γ and less IL-7, while IL-2, IL-6, IL-10, IL-12p70, IL-33 and CCL19/MIP-3 were unchanged." (PMID 38424104, 2024). "Patients with severe COVID-19, as evidenced in our study, release a large amount of pro-inflammatory cytokines (IFN-α, IFN-γ, IL-1β, IL-6, IL-12, IL-18, IL-33, TNF- α, and TGF- β)." (PMID 37408032, 2023). "This study provides novel insights into the role of alarmin cytokines, specifically IL-33, IL-25, and TSLP, in COVID-19." (PMID 37761861, 2023).
COVID-19 (continued). "A significant positive correlation was found only between IL-33 levels and the OPS scale (r = 0.289, p = 0.046) in persons diagnosed with COVID-19." (PMID 37759873, 2023). "This includes examining the circulating levels of sST2 in the blood and investigating the expression of IL-33 and ST2 genes in the heart of COVID-19 patients." (PMID 37568870, 2023). "Although the p62 blood levels in COVID-19 patients at diagnosis were decreased, they were positively correlated with the amounts of TNF, IL-17, IL-10, and IL-33." (PMID 37174682, 2023). "We found that increased levels of Ang-II induced increased expression of the cytokines: IL-6, IL-10, IL-33, IL-28A and CD40L in the severe COVID-19 group." (PMID 38137381, 2023). "The antiviral IFN-α and proinflammatory TNF, IL-6, IL-8, IL-17, IL-33, and IFN-γ were elevated in COVID-19 patients at both time points, while IL-10 and IL-1β were increased at admission and one week later, respectively." (PMID 37174682, 2023). "Systemic levels of IL-1β, IL-6, IL-10, IL-23, IL-33 and Gal-1 were significantly higher in stage III of COVID-19 patients compared to stage I and II." (PMID 35075140, 2022). "Attenuating the IL-6, IL-33 and DAMP pathways while administering IL-1ra, IL-33r and, potentially, recombinant IL-38, seems to be the most promising strategy to combat severe COVID-19." (PMID 35563282, 2022). "While IFN-α and IFN-β were undetectable, IL-10, IL-17A and IL-18 were variably detected in COVID-19 BALF, with higher RNA and/or protein levels of IL-6, MCP-1 and IL-33 and lower IL-6 receptor (IL-6R) observed in COVID-19 BALF compared to healthy BALF19,20." (PMID 35589689, 2022). "Analysis revealed a stronger positive correlation between the serum values of IL-33 and TNF-α (p = 0.000), IL-1β (p = 0.000), IL-6 (p = 0.000), IL-12 (p = 0.000), and IL-23 (p = 0.000) in COVID-19 patients with severe disease." (PMID 34917631, 2021). "Our results revealed a stronger positive correlation between serum values of IL-33 and innate immunity mediators TNF-α, IL-1β, IL-6, IL-12, and IL-23 in the severe form of COVID-19." (PMID 34917631, 2021). "These included IL-33, IFN-α2, IFN-λ3, IFN-β and IFN-γ, which were decreased in the nasopharynx of patients with COVID-19, while IL-10 and CCL2 were increased, as compared to healthy controls." (PMID 34471264, 2021). "IL-33, MCP-1/CCL2, and MIP-1α/CCL3 were also elevated in ICU status COVID-19 subjects over controls, consistent with other reports." (PMID 34960684, 2021). "Many of these cytokines, including IL-6, IL-18, IL-33, MCP-1, and MIP-1α, were elevated in the COVID-19 ICU and/or in-hospital mortality groups in our study." (PMID 34960684, 2021). "We also detected an increase in IL-33 and MCP-1 in the COVID-19 ICU group over controls (FDR < 0.05)." (PMID 34960684, 2021). "In fact, patients with COVID-19 had augmented values of HMGB-1 and IL-33 while facing lung injury or fibrotic processes." (PMID 34042528, 2021). "We used a multiplex cytokine assay to measure serum IL-6, IL-8, TNF, IL-1β, GM-CSF, IL-10, IL-33 and IFN-γ in 100 hospitalised patients with confirmed COVID-19 at admission to University Hospital Southampton (UK)." (PMID 32962703, 2020). "Given that IL-33 was responsible for the enhanced expression of CD25 and CD132 on IL-3–primed basophils in our in-vitro experiments, we next evaluated the expression of IL3 and IL33 in BALF cells from COVID-19 patients." (PMID 41459501, 2025). "In parallel, we observed a similar expression pattern of IL-2 receptors in COVID-19 patients, where basophils from severe cases showed upregulation of CD25 and CD132, but not CD122, a profile that correlated with elevated levels of IL-3 and IL-33." (PMID 41459501, 2025). "However, they also identified alarmins, such as IL-25, IL-33, and TSLP, which they suggested were likely to contribute to lung inflammation during different phases of disease progression in COVID-19." (PMID 37631998, 2023).
COVID-19 (continued). "Most previous studies were concerned with examining systemic concentrations of IL-22 and IL-33 in patients with severe/critical COVID-19, while data for mild/moderate cases are not overwhelming." (PMID 36875710, 2023). "Infected alveolar epithelial cells are the main source of IL-33 in the lungs, and activated SARS-CoV-2-derived papain-like protease can efficiently promote these cells to secrete IL-33, particularly in patients with severe COVID-19." (PMID 36875710, 2023). "We also observed significantly elevated levels of IL-33 and IL-25 proteins in COVID-19 patients compared to non-COVID individuals." (PMID 37761861, 2023). "IL-33 is believed to be involved in cytokine storms induced by a variety of pathogens, including influenza virus, Group A Streptococcus (GAS), LCMV virus, COVID-19, and so forth." (PMID 37842289, 2023). "The IL-31/IL-33 axis has emerged as a key player in the immune response against SARS-CoV-2, and further research is needed to fully understand its potential as a therapeutic target for COVID-19." (PMID 37240091, 2023). "This increase in sST2 concentration in the blood may impair the protective roles of the IL-33/ST2L system in the heart, leading to myocardial remodeling and potentially worse outcomes in COVID-19 patients." (PMID 37568870, 2023). "Our research showed elevated calpain 1 activity and IL-33 concentration in the serum of COVID-19 patients who developed ARDS compared to those who did not develop ARDS and a positive correlation between them was established." (PMID 37509486, 2023). "Our study showed increased calpain 1 activity and IL-33 concentration in the serum of COVID-19 patients who developed ARDS compared with those who did not, with a positive correlation between these two values." (PMID 37509486, 2023). "The concentration of alarmin cytokines IL-33, TSLP, and IL-25 were compared in COVID-19-positive and -negative patients, and the association of alarmin cytokine levels with disease severity and age-related variations was evaluated." (PMID 37761861, 2023). "Moreover, p62 modulation by NSP5 and ORF3a in vitro was involved in the regulation of TNF, IL-1, IL-6, IL-10, and IL-33 mRNA expression in THP-1 monocytic cell line, indicating a proinflammatory role of this autophagy receptor in COVID-19." (PMID 37174682, 2023). "In stage III of COVID-19 patients, moderate positive correlation was noticed between Gal-1 and IL-1β (p = 0.001) and IL6 (p = 0.005) and strong positive correlation between Gal-1 and IL-10 (p = 0.001), IL-23 (p = 0.001) and IL-33 (p = 0.001)." (PMID 35075140, 2022). "Other anti-inflammatory agents were also tested in their effectiveness by repurposed drugs for COVID-19 therapy and involved positive results under mediators such as inhibitors of C5, IL-1, JAK1, JAK2 and IL-33 and related to reducing release of TNF-α and IL-1β." (PMID 35843719, 2022). "The aim of this study was to determine the association of Gal-1 and innate immunity cytokines such as IL-1β, IL-6, IL-10, IL-23, IL-33 with disease severity, alongside with clinical, biochemical features and Chest X-rays (CXR) lung findings in 210 patients with COVID-19." (PMID 35075140, 2022). "Since the TLR7 pathway is required for recognition of the SARS-CoV-2 genome and production of IFN-I, the IL-33/ST2 axis may suppress innate antiviral immunity and delay viral clearance in COVID-19 patients by reducing IFN-I expression." (PMID 36362440, 2022). "PIMS-TS children had significantly elevated levels of cytokines, IFNγ, IL-2, TNFα, IL-1α, IFNα, IFNβ, IL-6, IL-15, IL-17A, GM-CSF, IL-10, IL-33 and IL-Ra; elevated chemokines, CCL2, CCL19, CCL20 and CXCL10 and elevated VEGF, Granzyme B and PDL-1 in comparison to COVID-19, seropositive and controls." (PMID 33813138, 2021). "Cytokines IL-18 and IL-33 were higher and IL-1β was lower in COVID-19 non-ICU patients versus controls (FDR < 0.1 or < 0.05)." (PMID 34960684, 2021).
COVID-19 (continued). "On the other hand, IL-33 increased moderately in critically ill COVID-19 patients but did not change in deceased ones." (PMID 34441830, 2021). "In the milder stage of COVID-19, a positive correlation was detected between IL-33 and IL-1β, IL-12 and IL-23, while a stronger positive correlation between the serum values of IL-33 and TNF-α, IL-1β, IL-6, and IL-12 and IL-23 was detected in patients with COVID-19 with severe disease." (PMID 34917631, 2021). "One of the cytokines that have not been sufficiently studied in the immunopathogenesis of COVID-19 is IL-33." (PMID 34917631, 2021). "Levels of IL-5 were not significantly influenced by SARS-CoV-2 infection, whereas IL-33 was increased in patients with severe and critical COVID-19 but not in patients who died from COVID-19." (PMID 33232303, 2021). "In this study, interestingly, mild/asymptomatic COVID-19+ pregnant women exhibited significantly elevated levels of proinflammatory cytokines/chemokines such as INF-α2, INF-γ, MCP-1, IL-6, IL-12p70, IL-17A, IL-18, IL-23, and IL-33, and the anti-inflammatory cytokine IL-10." (PMID 40303405, 2025). "In the COVID-19+ group, as expected, significantly increased levels of proinflammatory cytokines/chemokines including INF-α2, INF-γ, MCP-1, IL-6, IL-12p70, IL-17A, IL-18, IL-23 and IL-33 were detected, while the level of IL-10, an anti-inflammatory cytokine was also elevated as compared to controls." (PMID 40303405, 2025). "However, the potential role of IL-33 in the immunopathogenesis of COVID-19 has not been well detailed, but it is suggested that IL-33 plays a fundamental role in lung homeostasis." (PMID 36875710, 2023). "Overall, our findings suggest that alarmin cytokines (IL-33, TSLP, and IL-25) could serve as potential therapeutic targets to modulate disease severity in COVID-19, and genetic variations influencing protein production can also protect against developing severe COVID-19." (PMID 37761861, 2023). "Therefore, the current study aimed to analyze serum IL-22 and IL-33 concentrations in non-hospitalized patients exposed to mild/moderate COVID-19." (PMID 36875710, 2023). "The ability of IL-33 to activate both the IL-33/p38/GATA3 and IL-33/MAPK/STAT3 pathways suggests that IL-33 plays a key role in the regulation of ILC2 in pulmonary inflammation, which provides a new perspective for research into the mechanism of the secondary pulmonary symptoms of COVID-19." (PMID 36362440, 2022). "Not surprisingly, IL-33 may play both a deleterious and protective role in COVID-19 by regulating CD4+ T cells." (PMID 36362440, 2022). "Increased levels of the checkpoint cytokines IL-33 and ILC2 frequencies were detected in the serum and plasma of patients with moderate COVID-19, while decreased ILC2 frequencies were observed in severe patients, indicating that ILC2 may be involved in COVID-19 pathology." (PMID 36362440, 2022). "IL-33 and ST2 are widely expressed throughout the human body, and low plasma or serum levels of IL-33 or high levels of sST2 are seen in numerous diseases, including cardiovascular diseases, particularly heart failure and stroke, and infectious diseases, including sepsis and recently COVID-19." (PMID 35800259, 2022). "However, whether the IL-33/MAPK/STAT3/IL-13 axis plays a positive or negative role in the pathology of COVID-19 requires further exploration." (PMID 36362440, 2022). "We have found that, in patients in whom there was a clinical deterioration following SARS-CoV-2 infection, the initial inflammatory response in the airway is blunted with reduced concentrations of IL-2, IL-33, IL-12, and IFN-α2a, in comparison with patients with COVID-19 without deterioration." (PMID 35397798, 2022).
Sepsis (89 papers, 2008 to 2025). Sepsis is defined as life-threatening organ dysfunction caused by a dysregulated host response to infection. "Several studies have shown that expression levels of IL-33 or sST2 are elevated in the serum of patients with sepsis, suggesting that the IL-33/ST2 axis is associated with sepsis progression." (PMID 39925809, 2025). "In summary, the C allele of the AQP3 polymorphism (rs17553719) shows an association with increased AQP3 expression and IL-33 concentration accompanied by decreased survival in patients with sepsis." (PMID 38338680, 2024). "In a cohort of 152 neonates at risk of early-onset sepsis, serum IL-33 was an independent predictor of sepsis, with greater predictive power when combined with progranulin and procalcitonin." (PMID 36769133, 2023). "The results of our research showed that the values of IL-33 were significantly higher in the group of patients with sepsis caused by peritonitis, pancreatitis, and trauma compared to the control population of patients who had only trauma (p < 0.05)." (PMID 38152329, 2023). "Administration of AMD3100, a CXCR4 antagonist, largely induces ILC2 egress, which is blocked in IL-33 deficient mice during sepsis." (PMID 35272622, 2022). "In another study, IL-33 deficiency aggravated sepsis-induced lung injury, while supplementation with IL-5 reversed this effect in IL-33 knockout mice, suggesting that IL-33 participates in the process of sepsis-induced lung injury by regulating IL-5 release." (PMID 33628366, 2021). "We studied the mechanism underlying the effect of sesamin on the pathophysiology of sepsis through the HMGB1/TLR4/IL-33 signalling pathway." (PMID 32893702, 2020). "In this study, we evaluated the effect of IL-33 on septicemia and the underlying mechanisms by establishing a Staphylococcus epidermidis (S. epidermidis)-induced septicemic mouse model." (PMID 33178181, 2020). "Further investigation to determine blood neutrophils versus eosinophils ratio in patients with sepsis-associated AKI will help to decipher the contribution of the IL-33/ILC2 axis in the patient population." (PMID 32102434, 2020). "The current study demonstrated that IL-33 was increased in septicemic mice and exerted great predictive value for septicemia risk in the early phase." (PMID 33178181, 2020). "IL-33-mediated immunosuppression is reported to be associated with sepsis-induced immunosuppression." (PMID 32102434, 2020). "It has been observed that mice deficient in the receptor for IL-33 show improved survival post sepsis compared to naïve wild-type mice." (PMID 33336293, 2020). "The ability of IL-33 to improve survival during sepsis is linked to the rescue of neutrophil migration to the site of infection, to improvements in bacterial clearance, and to a reduction in lymphocyte apoptosis." (PMID 31507598, 2019). "IL-33 is implicated in the induction and maintenance of immunosuppression during sepsis through the induction of Tregs." (PMID 31507598, 2019). "On the other hand, elevated level of IL-33 is strongly involved in prolonged immunosuppression during the recovery of sepsis which is associated with IL-10 dependent enhancement of regulatory T cell expansion." (PMID 30001716, 2018). "We demonstrated that deficiency of either Il-33 or Il1rl1 prevented ILC2 expansion in the lungs following sepsis." (PMID 29511181, 2018). "Taken together, these data demonstrate a robust macrophage reprogramming toward an M2 phenotype in sepsis-surviving mice induced by type 2 cytokines and IL-33, presumably associated with the development of a wound healing response." (PMID 28374774, 2017). "Similar to IL-33, sST2 has been linked to the pathogenesis of various inflammatory conditions, including sepsis, asthma, autoimmune diseases, and cardiovascular diseases." (PMID 22778496, 2012).